LONRF3 (LON peptidase N-terminal domain and ring finger 3)
Synonyms: RNF127; FLJ22612
Tractability: Antibody: the Human Protein Atlas places it where antibodies can reach. PROTAC: ubiquitination databases record sites on it.
Gene: Protein-coding gene on chromosome X (118,974,614 to 119,022,925, forward strand). Ensembl gene ENSG00000175556.
Subcellular location (Human Protein Atlas): Nucleoplasm; Plasma membrane
Gene Ontology:
Molecular function: protein binding; ubiquitin protein ligase activity; metal ion binding
Homologues: Orthologues: chimpanzee LONRF3 (99% identical), macaque LONRF3 (98% identical), pig LONRF3 (88% identical), dog LONRF3 (86% identical), rat Lonrf3 (81% identical), mouse Lonrf3 (80% identical), rabbit LONRF3 (53% identical), tropical clawed frog lonrf3 (49% identical), guinea pig Lonrf3 (48% identical), Drosophila melanogaster CG32369 (27% identical), Caenorhabditis elegans T02C1.1 (7% identical). Paralogues in human: LONRF2 (40% identical), LONRF1 (35% identical).
Diseases named in the same sentence as LONRF3 in open-access papers:
LONRF3 is named in the same sentence as 5 diseases in open-access papers, as found by Europe PMC text mining. Sharing a sentence is not in itself a finding about the gene and the disease. The quoted sentences say what the papers report.
Alzheimer disease (1 paper, 2025). A progressive, neurodegenerative disease characterized by loss of function and death of nerve cells in several areas of the brain leading to loss of cognitive function such as memory and language. "Lonrf3 has been associated with Alzheimer’s disease and pancreatic cancer." (PMID 40356894, 2025).
cervical cancer (1 paper, 2022). A primary or metastatic malignant neoplasm involving the cervix. "In the present study, the immune subtype-relevant signature (covering TMEM125, TFF1, DECR2, LONRF3, DAPL1, and ANKRD35) was quantified, which predicted cervical cancer recurrence accurately and independently." (PMID 36313466, 2022).
dementia (1 paper, 2024). Loss of intellectual abilities interfering with an individual's social and occupational functions. "The classification performance of seven core DEGs identified in SAH and dementia was evaluated, with ROC curve analysis demonstrating their strong discriminative capabilities, particularly PAPOLA in dementia with an AUC of up to 0.989, followed by DOK3, LONRF3, and MILR1, all exceeding 0.900." (PMID 39726593, 2024).
LONRF3 also shares sentences with these, for which no sentence is quoted: cancer (1 paper); pancreatic cancer (1).